CD86 (CD86 molecule)
Diseases named in the same sentence as CD86 in open-access papers (continued):
Sharing a sentence is not in itself a finding about the gene and the disease.
tumor (continued). "We cocultured PDAC tumor cells with FMS‐like tyrosine kinase 3 ligand (Flt3L‐induced DCs, consisting of a mixture of cDC1 and cDC2 cells, and then the expression of costimulatory molecules CD80 and CD86 on DCs were examined." (PMID 35064757, 2022). "Interestingly, we observed that treatment with oxaliplatin (3.0 mg/kg, i.v.)significantly increased the populations of CD86+CD80+ and CD8+CD45+ cells in the tumor tissues as compared to the control and cisplatin-treated groups." (PMID 36131787, 2022). "Immune infiltration and immune checkpoints suggest that in cluster 1 there is an increased number of highly infiltrated CD86 and LAG3 cells, which are more active in boosting inflammation, and that CD44 has a higher activity and is more able to promote tumor metastasis." (PMID 36186475, 2022). "All the treatments including OVA resulted in expressions of CD40 and CD80 but not CD86 in tumor-derived macrophages." (PMID 36551577, 2022). "Furthermore, we found that CSF-1R was significantly correlated with tumor-related immunosuppressive molecules (including PDCD1, CTLA4, CD80, CD86, HAVCR2)." (PMID 35444953, 2022). "However, the expression pattern, correlation with tumor-infiltrating lymphocytes, and prognostic value of CTLA-4 and CD86 in RC after nCRT/nCT are yet to be further elucidated." (PMID 36428666, 2022). "Interactions between DC-expressing molecules (major histocompatibility complex (MHC) proteins loaded with tumor antigens and costimulatory molecules (CD80, CD86)) with T cell-expressing receptor (TCR), coreceptors (CD4, CD8), and CD28 are necessary for optimal activation of T lymphocytes." (PMID 35757015, 2022). "However, co-culture of the ORFV NA1/11-infected tumor cells with DCs significantly enhanced CD80 and CD86 expression on DCs, consistent with the notion that ORFV NA1/11-infected tumor cells enhanced the activation of surround DCs." (PMID 35959371, 2022). "Moreover, B cells in TLSs can function as antigen-presenting cells; they highly express the co-stimulatory molecules CD86 and CD80 and facilitate tumor antigen-specific T-cell responses, including CD8+ TIL and CD4+ TIL responses." (PMID 35663939, 2022). "Cytotoxic T lymphocyte-associated antigen-4 (CTLA-4), also known as CD152, is a membrane protein expressed on CD4+ and CD8+ T cells that is involved in the downregulation of T cell immune response at the tumor site upon interaction with CD80/B7.1 and CD86/B7.2 on APC." (PMID 35625811, 2022). "Moreover, this biocomplex regulated the secretion of tumor-related cytokines (i.e., GM-CSF, TNF, and IL-6) and promoted the activation of immune cell surface markers (i.e., CD80+, CD86+, and CD40+)." (PMID 36059807, 2022). "Moreover, low existence of CD86+ TAMs and high presence of CD206+ TAMs were outstandingly related with invasive tumour phenotypes and with poorer overall survival (OS) as well as reduced time to recurrence." (PMID 34964155, 2022). "In order to observe the number and location of CD86+ and CD206+ macrophages in the tumor microenvironment under GSK126 and EPZ6438 treatment, we performed multiplex immunofluorescence (mIF) assays to observe F4/80, CD86, and CD206 with the Opal staining technique." (PMID 35432300, 2022). "At 12 hours after injection, which is the time point before DC migration to TDLNs or MEDI9197-mediated tumor apoptosis occurred, the mcMEDI group showed significantly increased frequencies of activated DCs (CD86+) and T cell subpopulations (CD69+) in the tumor tissue." (PMID 35579961, 2022). "We guess that these co-expressed CD206 and CD86 macrophages do not have an anti-tumor effect, and the proportion of these macrophages will also increase with the increase of tumor volume." (PMID 35432300, 2022). "Therefore, the spleens of tumor-bearing mice after different therapies were collected and measured by flow cytometry to evaluate the variation of mature DCs (CD11c+, CD80+, CD86+)." (PMID 35812418, 2022).
tumor (continued). "In conclusion, tumor immunity was different according to the neoadjuvant therapy method and response, with CD86, CD4, and t/iCD8 expression, but not CTLA-4 and sCD8 expression, being significantly higher in the nCT-treated and poor response groups." (PMID 36428666, 2022). "Anti‐Chi3L1 antibody‐treated tumor tissues promoted ARG1 and CD206 expression inhibition compared with vehicle‐treated tumor tissues but did not change iNOS and CD86 expression." (PMID 34861103, 2022). "In addition, DCs in the tumor and dLNs demonstrated a significant increase in maturation marker expression including expression of MHC class II (I-Ab) and costimulatory ligand CD86 (B7-2)." (PMID 35972798, 2022). "These three modules contained recognized immune-related genes, such as CD86 and CD226, which have been reported to increase the downstream activation of NF-κB and CXCL9 whose secretion recruited CD8+ T cells into the tumor bed." (PMID 35237300, 2022). "Next, we evaluated the populations of CD86+CD80+ and CD8+CD45+ cells in the tumor tissues." (PMID 36131787, 2022). "The free drug and SPIND2 injection did not obviously increase the population of matured DCs (CD80+CD86+) in tumor-draining lymph nodes (TDLNs) compared to the saline control group." (PMID 35821238, 2022). "KDs increased tumor-reactive immune responses, including tumor infiltration of cytotoxic CD8+ T cells in malignant glioma mouse model and reduced the expression of T cell co-inhibitory receptors CTLA-4 and PD-1 and their ligands CD86 and PD-L1." (PMID 36432618, 2022). "Furthermore, immunohistochemical staining showed that the expression levels of CD86 and CD206 were also higher in orthotopic tumours treated with 231-EVs than those with 231/si-EVs or PBS." (PMID 35453742, 2022). "This could also be readily observed through comparison of the number of cells that expressed the macrophage markers CD68, CD86, and CD163 in paired human tumor lesions and adjacent normal tissue in the same tissue block." (PMID 35326625, 2022). "In the immune-resistant tumor model, these RNA NPs activated high levels of PDL1+ CD86+ myeloid cells, indicating that extensive immune activation of tumor-loaded RNA-NPs, accompanied by inducible PD-L1 expression, could be used for treatment." (PMID 35497343, 2022). "None of the treatments had any effect on CD40, CD80, or CD86 expression on DCs isolated from the tumor while the combination treatment significantly increased the MHC I antigen presentation on these cells." (PMID 36551577, 2022). "We propose that these cells might have a role in antigen presentation and activation of T lymphocytes in the tumour microenvironment, because of expressed MHCII, CD86 and CD80 markers." (PMID 36551739, 2022). "Preclinical studies using murine tumor models have indicated an increase in the number of activated dendritic cells (APCs) as evidenced by increased expression of MHC class II, CD80, and CD86, as well as increased levels of IL-12 and IFNγ in the tumor microenvironment post HIFU." (PMID 35848421, 2022). "BM-DCs that express dysfunctional β2-integrin have enhanced tumor rejection capabilities in B16.OVA and B16-F10 melanoma models and higher levels of expression of CD86, Il12, ccr7, and Fscn1, which are indicative of improved co-stimulation and migration capacity." (PMID 35267487, 2022). "Accordingly, significant activation (MHCII+, CD86+) of DCs (CD45+CD11c+) in dLNs and expansion of CD8+ T cells (CD45+CD3+CD8+) in dLNs, spleen, and tumors were achieved when poly(I:C) and tumor cell lysates were incorporated in the HGs administered s.c. to the tissue i.l. to the tumor." (PMID 36559246, 2022). "Indeed, co-culture of DCs with ORFV NA1/11-infected tumor cells engulfed more tumor cells than with uninfected tumor cells, and DCs exhibited high levels of CD80, CD86 and MHC I expression." (PMID 35959371, 2022).
tumor (continued). "Through co-culture experiments with immune cells, we demonstrated the increase of (i) CD86 maturation marker on dendritic cells, (ii) CD69 activation marker on cytotoxic T cells, and (iii) phagocytosis of tumor cells following treatment with SIX2G, confirming the onset of an immunogenic cascade." (PMID 36142133, 2022). "For optimal T-cell–mediated anti-tumor immunity, T cells must recognize an antigen presented on major histocompatibility complexes (MHC) through the T-cell receptor (TCR) and receive a co-stimulatory signal through CD28 engagement with CD80/CD86." (PMID 36248881, 2022). "Therefore, increased presence of tumor-infiltrated CD80 and CD86-expressing DCs ensures optimal and successful generation of effector, tumoricidal T cells which would, upon activation, infiltrate the tumor tissue to eliminate cancer cells." (PMID 35757015, 2022). "On the other hand, the VM index could upregulate immune checkpoints including CD28, CD86, BLTA and CD40LG to inhibit immune response, thus leading to tumor immune escape." (PMID 36505458, 2022). "Interestingly, tumor-induced Bregs express high levels of CD80 and CD86, suggesting that CD80 and CD86-mediated contacts between Bregs and their target cells are essential for suppressing T cell response and Bregs-induced Tregs differentiation." (PMID 33767709, 2021). "The M1 macrophages produce pro-inflammatory factors (TNF-α, IL-1β, and iNOS), chemokines (CXCL10, CXCL11, and CCL2), antigen-presenting molecules such as MHCII, costimulatory molecules (CD86 and CD80), and antigen-treated peptidases, which play an anti-tumor role in cancer." (PMID 34034714, 2021). "Analysis of tumor immunity and GSEA revealed pivotal role of CD86 in immune response for LGG." (PMID 33954112, 2021). "Moreover, antigen presenting cells (APCs) from Osm−/− tumours expressed higher levels of co-stimulatory molecules such as CD40 and CD86." (PMID 34921158, 2021). "CYT levels were significantly associated with tumor immune response factors, such as CD19, CD86, LTA, HLA-B, LAG3 and A2AR, in primary tumors but not in metastatic sites (lower row)." (PMID 33476333, 2021). "It increased dendritic cells (DC)s and CD4+ and CD8+ T cells, decreased B cells, induced the secretion of Th1 cytokines and IL-2, increased IFN-γ levels, and promoted DC maturation (CD86+ MHCII; higher levels of IL-12p40 and IL-12p70 were recorded, as was the inhibition of tumor growth." (PMID 33435246, 2021). "Mature DCs loaded with PAM lysates showed an increased maturation potential, as estimated by their increased expression of CD83, CD86, CD40, IL-12/IL-10 production, and attenuated PDL1 and ILT-4 expression, compared to the DCs treated with control tumor lysates." (PMID 33915703, 2021). "Moreover, we demonstrate that monocytes co-cultured with tumor cells or the decellularized tumor matrix (D-ECM) differentiate toward a pro-tumoral macrophage phenotype with low expression of MHC-II and CD86 and strong expression of CD206." (PMID 34680345, 2021). "Engagement of B7 ligands, notably B7-1 (CD80) and B7-2 (CD86), on antigen-presenting cells with CD28 co-stimulatory receptors on T cells stimulates the proliferation and activation of CTLs, which subsequently elicits an anti-tumor immune response in the host." (PMID 34541363, 2021). "We hypothesized that low CD86+ and high CD163+ TAM levels were clearly correlated with aggressive tumor phenotypes." (PMID 34512652, 2021). "Importantly, POLD1 expression was associated with immune checkpoint molecules, including CD274, CD80, CD86, CTLA4, PDCD1 and TCGIT, and facilitated an immune-excluded tumor microenvironment." (PMID 34868924, 2021). "Strikingly, the higher dose of exosomes derived from LOAd703-infected tumor cells could mature DCs, as seen by upregulation of MHC class I (HLA-ABC), CD86, and CD83 (p ≤ 0.05)." (PMID 33738337, 2021). "There was also similar expression of Cd80, Cd86, Fcgr1, Fcgr3 and Fcgr4 in the tumor tissues (data not shown)." (PMID 34774008, 2021).
tumor (continued). "Given that CD86 and HLA-G are transferred from tumor cells via trogocytosis, trogocytosis of these molecules by CD8+ T cells may play a suppressive role in tumor immune responses." (PMID 34069602, 2021). "Given their expression of PVR, TNFRSF14 and CD80/CD86, they might be under direct control by TIGIT+CTLA4+CSF2+TNFSF14+ tumor cells." (PMID 33968070, 2021). "It has been suggested that TAMs with an M2-like phenotype (markers CD163, CD204, and CD206) have a pro-tumor effect while M1-like TAMs (CD68, CD80, and CD86) may have an anti-tumor effect." (PMID 33882057, 2021). "Importantly, the tumor antigen peptide-MHC complex and costimulatory factors, such as CD86, are expressed at high levels on the surface of mature DC-derived EVs, which can be presented to immune cells to activate TAA-specific effector T cells." (PMID 34956197, 2021). "Although CD86 expression was significantly altered among different tumor stages in SKCM, no independent prognostic value in OS was observed." (PMID 33954112, 2021). "Similarly, PIR-B or PD-L1 inhibition reduced the proportion of CD206+ and CD163+ TAMs but elevated that of CD86+ and CD80+ TAMs in tumor tissues with the most obvious alteration in the combined blockade group." (PMID 33537094, 2021). "The levels of molecules representing the function of M1 macrophages, such as CD86, MHC II, CXCL10, and IL-12, were markedly increased in the cryo-thermal therapy with sEV injection group compared to that from the tumor-bearing and cryo-thermal therapy-treated mice." (PMID 34681680, 2021). "Monocytes co-cultured with tumor cells or a decellularized tumor matrix differentiated toward a pro-tumoral macrophage phenotype characterized by decreased expression of MHC-II and CD86 and increased expression of CD206 and an abundant release of pro-tumoral cytokines and chemokines." (PMID 34680345, 2021). "Taken together, these results suggested that CTLA4-T cells confer strong anti-tumor activities and could specifically suppress CD80/CD86-expressing tumors in vivo." (PMID 33868277, 2021). "Moreover, the authors showed that RES effectively stimulated the infiltration of high level of DCs (CD80+/CD86+) and cytotoxic CD8+ T-cells into tumor tissue of xenograft tumor model established with ID8 cells." (PMID 33440842, 2021). "CD86 demonstrated to be an unfavorable factor independent of clinicodemographic variables in tumor progression and prognosis for LGG, which was validated by qRT-PCR and WB in LGG samples, as well as a real-world cohort in CGGA." (PMID 33954112, 2021). "For other CD80/CD86-negative solid tumors, it is worthy of consideration to utilize CAR construct targeting the tumor-associated antigens as well as converting CTLA4 signals." (PMID 33868277, 2021). "Flt3L did not affect the activation state of tumor-infiltrating cDC1s, because it did not affect the levels of CD40, CD86 or MHCII in tumor-infiltrating cDC1s." (PMID 33810248, 2021). "Herein, we revealed that tumor cells and the decellularized tumor matrix induce the differentiation of monocytes in macrophages, characterized by high surface expression of CD206 and reduced expression of MHC-II and CD86." (PMID 34680345, 2021). "Notably, infiltrating immune and tumor cells present immunosuppressive molecules, such as programmed death-ligand 1 (PD-L1) and CD80/CD86." (PMID 33406733, 2021). "Combined with our TAM sub-clustering results, these results indicated that CD86+ TAMs could secrete CCL3 and play a positive role in tumor development." (PMID 33971970, 2021). "To reinvigorate CTLA-4-targeted immunotherapy, we and others have reported that rather than blocking CTLA-4 interaction with its cognate targets, CD80 and CD86, anti-CTLA-4 antibodies achieve their therapeutic responses through selective depletion of regulatory T cells in the tumor microenvironment." (PMID 31991588, 2020).
tumor (continued). "Next, we observed F4/80 (the marker of total macrophage) and CD86 (the marker of M1) by confocal laser scanning microscope, meanwhile, the level of GLUT1 and FBP1 were also detected to find out the hypoxia level and glycolysis level in the tumor." (PMID 32943999, 2020). "Interestingly, flow cytometry identified the CD86 and CD163 double-positive TAMs after co-culture with stably transfected CRC cells, indicating that tumor cells induced TAMs of a mixed M1/M2 phenotype." (PMID 32653013, 2020). "Notably, tumor-derived pDCs responded to TLR stimulation with upregulation of CD69, CD86, and CD83 after 4 h." (PMID 33013879, 2020). "It is unclear why CD86 expression was increased in the meninges, but not in the tumor or draining lymph nodes of FUS+MBs treated animals." (PMID 32754281, 2020). "First, we have reported that blocking the interaction between CTLA-4 and its cognate ligand CD80 and CD86 is neither necessary nor sufficient for anti-CTLA-4-induced tumor rejection." (PMID 31991588, 2020). "Further investigations are needed to delineate the role of (a) cellular components (regulatory cells, natural killer cells, etc.)that include costimulatory versus coinhibitory molecules, (b) molecular components (CD28, CD86, CD80, etc.), and (c) cellular mechanisms involved in anti-tumor response." (PMID 32326142, 2020). "In addition to roles in naïve T cell priming, CD80 and CD86 induce proliferation and IFN-γ expression in exhausted, tumor-specific CD8+ T cells within the TME following vaccination with moDCs." (PMID 31947933, 2020). "We have confirmed that indeed moDCs show maturation features when in the presence of supernatant of tumor cells treated with the highly cytotoxic NB-PDT, including upregulation of the maturation markers CD86 and MHC II and increased secretion of IL12-p40, IL-1β, and IL-10." (PMID 32326519, 2020). "Increased expression of HLA-DR by tumors in the absence of the co-stimulatory receptors CD80 or CD86, as one example, has been shown to suppress T-cell activation and tumor infiltration by lymphocytes." (PMID 32934776, 2020). "Moreover, BMDCs exposed to DACT‐treated tumor cells upregulated MHC class II and the co‐stimulatory molecule and activation marker CD86." (PMID 32323922, 2020). "Positive correlations between CD40‐expressing DC subsets were lost in patients, and negative correlations between CD80‐expressing DCs and CD86+ pDCs emerged in tumor infiltrates, which fits with impacts observed on clinical outcomes." (PMID 33282290, 2020). "In our settings, adding butyrate in mice treated with IgG2b did not induce modification of CD86/CD80 expression (in tumor-bearing mice)." (PMID 32358520, 2020). "The number of dendritic cells per tumor area was significantly higher in EBVaGC cases than in EBV-negative GC cases for any of the DC markers (p < 0.001 for Langerin, CD1a, CD83, CD86, and BDCA-2, and p < 0.05 for S100, respectively, determined by using a Wilcoxon rank sum test)." (PMID 33198173, 2020). "Monocyte-derived DCs (moDCs) were incubated with the conditioned medium of tumor cells treated with NB-PDT and the expression of two maturation markers, MHCII (an antigen presenting molecule) and CD86 (a costimulatory molecule), on the surface of moDCs was evaluated." (PMID 32326519, 2020). "The expression of the immunogenicity marker CD86 was also increased in the DAC-treated group and the DAC and OXP-treated group, suggesting that DAC may provoke tumor immunogenicity in vivo." (PMID 32079180, 2020). "Notably, Ocs-P administration restored the expression of CD80, CD86, and MHC-I in lineage-CD11c+MHC-II+ splenic DCs induced by tumor injection." (PMID 33105813, 2020). "Our results demonstrated that the expression of CD40, CD80, CD86, and HLA-DR was downregulated after coculture with H-1299 tumor cells compared with that on CD1c+ DCs that were not incubated with H-1299 cells." (PMID 31921114, 2019).